IL1A (interleukin 1 alpha)
Diseases named in the same sentence as IL1A in open-access papers (continued):
Sharing a sentence is not in itself a finding about the gene and the disease.
psoriasis (continued). "We found GPR15LG knockdown down-regulated the expressions of IL-1α, TNF-α, IL-1β and S100A7 in M5-treated HaCaT cells, suggesting a pivotal role of GPR15LG in keratinocyte-mediated inflammation in psoriasis." (PMID 38393364, 2024). "It has been previously demonstrated that a decrease in PPAR-alpha levels was observed in the lesional skin of patients with psoriasis and that topical PPAR-alpha agonist application decreased TNF-α and IL-1α in the skin." (PMID 38672088, 2024). "In our study, the strong increase of IL-1α, TNF-α, IL-1β and S100A7 was observed in psoriasis-like lesions." (PMID 38393364, 2024). "Proinflammatory cytokines IL-1α, TNF-α, IL-1β and S100A7 have been reported to be up-regulated in psoriatic skins and they are involved in the psoriasis pathogenesis." (PMID 38393364, 2024). "The combination of TNF-α, IL-1α, IL-17A, IL-22, and OSM (termed as M5) has been shown to induce psoriasis-like changes, including cell inflammation and increased cell proliferation in cultured keratinocytes." (PMID 36999136, 2023). "Our findings confirm that the skin surface hBD-2, IL-1α, CXCL-1/2, and CXCL-8 are markers for the psoriasis severity." (PMID 38003437, 2023). "Our results also show that IL-17A (a critical proinflammatory cytokine in the pathogenesis of psoriasis) induced increased glycolysis, lactate production, and psoriasis-related factors, including the expression of CXCL1/2 and IL-1α/β, in mouse primary KCs." (PMID 37303600, 2023). "Normal human epidermal keratinocytes (NHEKs), HaCaT cells, and Ker-CT cells stimulated with M5 (IL-17A, IL-22, IL-1α, oncostatin M, and TNF-α) were used to establish a psoriasis model in vitro." (PMID 35586566, 2022). "Our data show that eCIRP expression was increased in the sera of psoriasis patients and imiquimod- (IMQ-) induced psoriatic mice and cells stimulated with proinflammatory cytokines (IL-1α, IL-17A, IL-22, oncostatin M, and TNF-α; mix M5)." (PMID 36110097, 2022). "In the pathogenesis of psoriasis, PRINS inhibits the expression of cellular inflammatory factors [e.g., interleukin (IL)-1α, IL-1β, IL-6, IL-8, and tumor necrosis factor-α) and thus affects inflammatory responses." (PMID 36187126, 2022). "In this study, a combination of IL-1α, IL-17A, IL-22, oncostatin M, and TNF-α (mix M5) was used to trigger psoriasis-like changes in NHEK cells in vitro." (PMID 34314383, 2021). "Several cytokines are used for the generation of psoriasis-like HPK, i.e., IL-17A, TNF-α, IL-36γ, oncostatin, IFN-γ, IL-22 and IL-1α." (PMID 33801280, 2021). "Therefore, it is possible that increased levels of gut IL-1α in individuals with psoriasis may contribute to increased inflammation via the gut-skin axis and may help explain the well-documented epidemiological link between psoriasis and inflammatory bowel diseases." (PMID 33117362, 2020). "BAIAP2 has been shown to control the expression of the proinflammatory cytokines IL-6 and IL-1α, and PRKCZ has been noted to play a role in controlling inflammatory dermal mesenchymal stem cells in psoriasis, a T cell-mediated disease." (PMID 32117236, 2020). "The mixture of IL-17A, IL-22, oncostatin M, IL-1α, and TNF-α (M5) cytokines were used to simulate HaCaT keratinocytes to establish psoriatic keratinocyte model recapitulating some features of psoriasis in vitro." (PMID 33081840, 2020). "High abundance of these S100-proteins during psoriasis can be explained especially by the effects of IL-17A, IL-17F, TNF, and IL-1α on S100A8/S100A9 expression, which are all central players in the pathogenesis of psoriasis." (PMID 33643287, 2020). "HaCaT cells were stimulated with a cocktail of five proinflammatory cytokines (M5), including IL-1α, IL-17A, IL-22, oncostatin M, and TNF-α that has been demonstrated as an in vitro model of psoriasis." (PMID 33149756, 2020).
psoriasis (continued). "After silencing IL37, cells were stimulated with a mixture of five cytokines designated as M5 (IL-1α, IL-17A, IL-22, Oncostatin M, and TNF-α) to mimic the microenvironment of keratinocytes in psoriasis." (PMID 30918469, 2019). "NHEK were stimulated by A-SAA or the cytokines IL-1α, IL-17A, IL-22, OSM, TNF-α alone or in combination, previously reported to reproduce features of psoriasis." (PMID 28708859, 2017). "All the data mean that mature IL-1α, mS100a7a15 and calpain-1 are positive expressed in IMQ-induced psoriasis mouse model." (PMID 28060905, 2017). "Our attempt to model skin inflammation showed that the combination of IL-17A, IL-22, IL-1α, OSM and TNFα (Mix M5) synergistically increases chemokine and antimicrobial-peptide expression, recapitulating some features of psoriasis." (PMID 25010647, 2014). "Moreover, results from cytotoxicity and IL-1α release assay suggest DHNA causes less irritation problems than dithranol, which its use has declined because of its substantial skin irritation problems, but is still a popular and important topical treatment for psoriasis among European countries." (PMID 23690852, 2013). "We demonstrated that psoriasis-related transcripts, such as IFN-γ, TNF-α, IL-17A, CCL20, IL-23, IL-6, IL-1α and IL-22, were significantly enhanced in mouse ears treated with PL and rMCP-1 than those with 1×PBS control." (PMID 21311769, 2011). "To mimic an inflammatory milieu as found in psoriasis, we stimulated normal human keratinocytes with a mixture of interferon-γ, TNF-α and IL-1α (pro-inflammatory cytokines; further referred to as Th1 cytokine mix)." (PMID 18523683, 2008). "Interestingly, the psoriasis-related inflammatory factors, including TNF-α, IL-17, IL-22, OSM, and IL-1α, promoted YAP1 up-regulation in keratinocytes, as indicated by increased YAP1 expression (& f)." (PMID 40108109, 2025). "Furthermore, in an in vitro psoriasis model where normal keratinocytes were stimulated with the M5 cytokine cocktail (TNF-α, IL-17A, IL-22, IL-1α, and oncostatin M), DGAT2 expression was similarly reduced." (PMID 40694426, 2025). "The transcriptional expressions of Cxcl1, Cxcl2, Il-1β, Il-1α, S100A8, S100A9, Il-6, and Vegf were significantly decreased in skin lesions of K14.Bsgfl/fl mice, indicating the proinflammatory role of the epidermal expression of CD147 in psoriasis." (PMID 37303600, 2023). "IL-1α, IL-1RA, and CXCL-1/2 are cytokines directly involved in psoriasis skin inflammation." (PMID 36936209, 2023). "During the 4 weeks course of UVB treatment, levels of IL-1α Did Not change on the lesional skin of psoriasis patients, but there was a modest decline In IL-1α on non-lesional skin." (PMID 36936209, 2023). "Our results showed that ELE significantly inhibits the expression of IL1A, IL1B, IL6, and IL8 in M5-stimulated keratinocytes, demonstrating that ELE suppresses the inflammatory responses of psoriasis keratinocytes by attenuating the expression of various interleukins." (PMID 36467042, 2022). "Although the neutralization of IL-1RAcP affects the pathway induced by IL-1α, IL-1β and IL-33, its administration has positive effects in the control of the inflammation in OVA-induced allergic airway inflammation and Imiquimod-induced psoriasis." (PMID 34887860, 2021). "Mixed cytokines, including IL-17A, IL-22, oncostatin M, IL-1α, and TNF-α (M5), are used to simulate HaCaT keratinocytes in vitro to establish a psoriatic keratinocyte model that generates some common phenotypic features of psoriasis." (PMID 34202301, 2021). "Mixed cytokines, including IL-17A, IL-22, oncostatin M, IL-1α, and TNF-α (M5), were used to simulate HaCaT keratinocytes to establish a psoriatic keratinocyte model that generates some phenotypic features in common psoriasis in vitro." (PMID 34202301, 2021).
psoriasis (continued). "Smits and colleagues established psoriasis and atopic dermatitis models using N/TERT epidermal skin by adding Th1/Th17 (TNF-α, IL-6, IL-1α, IL-17, and IL-22) cytokines and Th2 (IL-4 and IL-13) cytokines, respectively, during the final stage of the skin maturation." (PMID 32509598, 2020). "In psoriasis, pro-inflammatory cytokines including IL-17A, IL-22, TNF-α and IL-1α may contribute to the pathophysiology of the disease." (PMID 30180891, 2018). "IL-1α also up-regulated NAMPT (visfatin), a pro-inflammatory cytokine elevated in psoriasis." (PMID 28323859, 2017). "Taken together, our results suggest that mature IL-1α induced by hS100A7 is via RAGE-p38 MAPK and calpain-1 pathway in keratinocyte and this mechanism may play an important role during psoriasis." (PMID 28060905, 2017). "The cutaneous expression of IL1A transcripts is reduced in inflammatory skin diseases like psoriasis or AD whereas no significant changes are seen for IL1B." (PMID 23531535, 2013). "Immunohistochemical, western blot, and multiplex analysis showed that the TLR activation induced the expression of psoriasis associated markers like S100A7, p-STAT3, CXCL-1, IL-8, IL-1α, S100A9, and IL-23 in the wild type but not in the TLR KO epidermis models." (PMID 40995100, 2025). "This study aimed to investigate the effects of IFN-γ and a cytokine mix (5MIX: IL-1α, IL-17A, IL-22, OsM, and TNF-α) on the antigen-presenting capabilities of keratinocytes, with a specific focus on immune-mediated dermatological conditions such as psoriasis (Ps)." (PMID 39769151, 2024). "This study aims to investigate the modulatory effects of IFN-γ and a proinflammatory cytokine mix (5MIX: IL-1α, IL-17A, IL-22, OsM, and TNF-α) on keratinocyte antigen-presenting capacities and their interactions with CD4+ lymphocytes, with a specific focus on their role in psoriasis pathogenesis." (PMID 39769151, 2024). "The analyses revealed that there was a clear molecular excess of IL-1α over IL-1RA on non-lesional skin of psoriasis patients and the skin of healthy volunteers, regardless of whether IL-1α was present in immature or in mature form or a combination thereof." (PMID 36936209, 2023). "The inverse expression patterns of IL-1α and IL-1IL-1RA on lesional and non-lesional skin of psoriasis patients, as well as the biological link between IL-1α and IL-1RA, prompted us to analyze the molar ratio between IL-1α and IL-1RA on lesional and non-lesional skin of psoriasis patients." (PMID 36936209, 2023). "Similarly, there was a clear excess of IL-1RA over IL-1α on the lesional skin of psoriasis patients regardless of the form of IL-1α." (PMID 36936209, 2023). "Because MAB-hR3 disrupts the recruitment of IL-1RAcP, other inflammatory signals mediated by IL-1α, IL-1β and IL-33 were also disrupted in vitro and in vivo models of local and systemic inflammation models in mice such as peritonitis, OVA-induced airway allergy and Imiquimod-induced psoriasis." (PMID 34887860, 2021). "IL-1α and IL-1β cytokines stimulate the release of chemotactic cytokines such as IL-8, either directly or in synergy with TNF-α and are involved in the pathologies of several skin diseases including psoriasis, cutaneous lupus erythematosus, atopic dermatitis, and autoimmune blistering diseases." (PMID 31001258, 2019). "Skin surface levels of IL-1α, IL-1RA, CXCL-1/2, and hBD-1 detected on the skin of healthy volunteers appeared similar to the levels captured on the non-lesional skin of psoriasis patients." (PMID 36936209, 2023). "Using TAP technology, it was observed that there were clear differences in levels of IL-1α, IL-1RA, CXCL-1/2, and hBD-1 between psoriasis lesional and non-lesional skin." (PMID 36936209, 2023). "Comparing the levels of skin surface IL-1α, IL-1RA, CXCL-1/2, and hBD-1 captured from psoriasis patients’ lesional and non-lesional skin revealed statistically higher levels of IL-1RA (p < 0.001), CXCL-1/2 (p < 0.01), and hBD-1 (p < 0.05) on lesional skin." (PMID 36936209, 2023).
psoriasis (continued). "In particular, serum levels of IL-17A were strongly correlated with IL-1α, IL-15, IFN-γ, IL-18, TNF-α, IL-12B, IL-17F, and IL-22 in psoriasis but not in healthy controls." (PMID 36118416, 2022). "A clear increased concentration of IL-1α, TNF-α and IL-6 was found in skin lavage from lesion sites of psoriasis patients, in comparison with skin lavage from non-lesional sites, or from skin of healthy individuals." (PMID 25785188, 2014). "However, notable differences were noticed in the amounts of IL-1α (3.14 vs. 0.98 ng/mL) and CXCL-1/2 (not detected vs. 0.06 ng/mL) when compared between healthy volunteers and lesional skin of psoriasis patients (p < 0.001 and p < 0.01, respectively)." (PMID 36936209, 2023).
periodontitis (91 papers, 2010 to 2026). An acute or chronic inflammatory process that affects the tissues that surround and support the teeth. "Such heterogeneity is consistent with findings in periodontitis, where IL-1α and IL-1β polymorphisms show population-specific associations influenced by ethnic background and environmental exposure." (PMID 41373620, 2025). "In fact, in a Turkish population, heterozygosity for allele 1 of IL-1α (+4845) or homozygosity for allele 1 of IL-1β (+3954) increases vulnerability to localized aggressive periodontitis." (PMID 41300760, 2025). "Among the host immune factors, interleukin-1 alpha (IL-1α) has been implicated in the pathogenesis of periodontitis." (PMID 39810806, 2024). "Only case-control and cross-sectional studies investigating the association between IL-1α polymorphisms (+4,845 and –889) and various forms of periodontitis in the Indian population were included." (PMID 39810806, 2024). "The aim of the current systematic review was to find the factors associated with IL-1α in causing periodontitis among Indians." (PMID 39810806, 2024). "Many studies have aimed to find the association between IL-1α and periodontitis in various populations worldwide." (PMID 39810806, 2024). "The link between IL-1α polymorphisms and periodontitis in the Indian population remains complex and heterogeneous, influenced by factors such as genetic diversity, environmental exposures, and disease subtypes." (PMID 39810806, 2024). "In Caucasians, the polymorphisms IL-1A −889T/C and IL-1B 3953/4 C/T are associated with chronic periodontitis." (PMID 39684335, 2024). "A meta-analysis that evaluated associations of genetic polymorphisms and periodontal disease revealed a greater frequency of IL-1a and IL-b polymorphisms for developing periodontitis; however, this association is variable between regions." (PMID 37998274, 2023). "As noted in Section 1.4, the tooth loss genotype, IL1A-889(A)+IL1B+3954(T) occurs at a frequency of 68% in hosts presenting with at least two of three periodontitis risk factors, smoking, diabetes, or teeth cleaned professionally twice or less per year." (PMID 37762554, 2023). "It has been demonstrated that there is low prevalence of the periodontitis-associated IL-1A (+4845) and IL-1B (+3954) gene polymorphisms in Chinese (2.3%) compared with that reported for Caucasians (36%)." (PMID 35855430, 2022). "Accordingly, a composite genotype, the so-called PST+ genotype, characterized by the simultaneous presence of IL-1A and IL-1B allele 2, was found to be related to greater severity of chronic periodontitis." (PMID 36429405, 2022). "In contrast, IL-1α −889C/T C allele also had a strong relationship with the periodontitis development with OR (95% CI), 0.75 (0.66–0.85)." (PMID 35046930, 2021). "Polymorphisms of IL-10 have been associated with those of tumor necrosis factor α IL-1α, IL-1β and IL-1RA in periodontitis." (PMID 34069916, 2021). "IL-1α −889C/T T allele had a favorable relationship in the prevention of periodontitis risk with OR (95% CI), 1.12 (0.99–1.25)." (PMID 35046930, 2021). "IL-1A allele 2 and IL-1B+3953 allele 2 genotypes were recognized as strong indicators for severe periodontitis in an adult populations." (PMID 33343358, 2020). "Genetic polymorphisms of IL-1α and IL-1β are likely to be related to an individual’s genetic susceptibility to periodontitis." (PMID 33081038, 2020). "The authors of another study found the associations between IL-1α gene −889C/T and IL-1β gene +3953C/T polymorphisms and early-onset periodontitis in African American and Caucasian populations." (PMID 33327639, 2020). "It has been reported several genetic variant in IL-1A gene associated to periodontitis but results are inconsistence." (PMID 27918732, 2017). "The meta-analysis showed the -889 C/T in IL-1A gene is associated to elevated risk development of chronic periodontitis." (PMID 27918732, 2017).